ALB (albumin)
Diseases named in the same sentence as ALB in open-access papers (continued):
Sharing a sentence is not in itself a finding about the gene and the disease.
diabetes (continued). "DOP was also used in a mouse model of diabetes, with the measurements of urine albumin, blood creatinine and blood urea nitrogen." (PMID 37812195, 2023). "The age, sex, BMI, comorbidities (hypertension, diabetes), and laboratory value (hemoglobin, total bilirubin and albumin) were used to evaluate the occurrence of Clavien-Dindo Score ≥3b after operation in univariate logistic regression analysis." (PMID 37066018, 2023). "The presence of GLIM malnutrition, LVEF, albumin, hypertension, diabetes mellitus, chronic obstructive pulmonary disease, and GFR were included in the logistic regression analysis." (PMID 37836479, 2023). "Gender, age, marital status, ethnicity, BMI, ARB, diuretics, PVD, COPD, diabetes, renal failure, hemoglobin, neutrophils, hematocrit, albumin, pH, lactate, glucose, PCO2, BE, OASIS, and SAPS were statistically different between groups divided by GNRI score." (PMID 37226575, 2023). "Adjusted for baseline data (age, sex, diabetes mellitus, serum potassium, serum albumin, constipation, use of PPI, daily ultrafiltration, and reduced LVEF) and follow-up data (BMI and urine volume)." (PMID 38123633, 2023). "Many patients in the studied group had an average albumin level of 28.9 g/L, showing the nutritional status of patients with diabetes and cancer." (PMID 37627906, 2023). "The logistic regression equation included five variables: diabetes, decompensated liver cirrhosis, long-term use of immunosuppressive agents, decreased serum albumin level, and elevated plasma cytokine IL-10 level." (PMID 38115055, 2023). "We also did not have important health indicators such as frailty, cognitive function, and functional status, but we stratified by albumin level and Hb status of patients with diabetes in our analysis." (PMID 36643628, 2023). "Urinary albumin excretion was significantly higher after 12 weeks of diabetes in both suramin-treated and untreated rats." (PMID 37834118, 2023). "Current research has linked an increase in the urine albumin-to-creatinine ratio (UACR), a marker for kidney damage, to a greater risk of adverse renal outcomes and ESRD in patients with diabetes." (PMID 37090383, 2023). "In summary, the most important predictors of survival without LT were age, MELD(-Na) score, serum sodium, serum AFP, serum albumin, presence of diabetes mellitus, presence of ascites, and liver disease aetiology." (PMID 38034881, 2023). "There was no statistical difference between male and female offspring for albumin excretion (AUC) or GSI after 18 weeks of diabetes (24 weeks of age)." (PMID 36695822, 2023). "This has implications for the clearance of waste proteins, LPS and other ligands normally cleared by SR-H, since elevated levels of oxidized albumin are seen in diseases such as atherosclerosis, diabetes and acute and chronic liver failure." (PMID 37926735, 2023). "The work herein presented a biosensor for detection of glycated albumin (GA), along with its exploitation as a biomarker for diabetes." (PMID 38125431, 2023). "We can conclude that in these cases, the main predictors are patients’ general conditions (in the present series, diabetes and postoperative albumin levels)." (PMID 37623473, 2023). "An effective weighted risk model was also developed to assess DKD progression to dialysis; the top six risk factors in the model were hemoglobin, HbA1c, neutrophil percentage, serum albumin, duration of diabetes, and plasma fibrinogen." (PMID 37308973, 2023). "Cox regression found an association between death and age (HR=1.051, 95% CI 1.026-1.07, p=0.0001) and albumin (HR=0.66, 95% CI 0.501-0.893, p=0.0064), and between peritonitis and a diagnosis of diabetes (HR=2.016, 95% CI 1.25-3.25, p=0.004)." (PMID 35788617, 2023). "In contrast, age, smoking, hypertension, diabetes, SCr, BUN, glucose, WBC and stroke patients were associated with lower serum albumin levels (all P < .05)." (PMID 37682189, 2023).
diabetes (continued). "Among the 4 quartiles of serum albumin levels, there were statistically significant variations in age, sex, race, education level, smoking, alcohol use status, BMI, diabetes, hypertension, UA, SCr, BUN, glucose, WBC, HDL-C, LDL-C and TG (all P < .05)." (PMID 37682189, 2023). "The association remained significant after adjustment for several potential risk factors, including age, history of coronary heart disease, history of diabetes, history of using statins, albumin, phosphorus, NT-proBNP and glucose." (PMID 37009921, 2023). "A total of 158 patients with type 2 diabetes mellitus were distributed into three groups according urinary albumin-to-creatinine ratio." (PMID 37822815, 2023). "In the present study, the SSI incidence in the 10% povidone‐iodine group was significantly higher in patients who underwent open surgery, with lower serum albumin, and with a prevalence of diabetes." (PMID 37663968, 2023). "Risk factors including demographic characteristics such as gender and age, comorbidities such as diabetes, and laboratory indicators such as albumin have also been pointed out and summarized in previous studies." (PMID 37051200, 2023). "Although serum creatinine was not significantly increased, hyperfiltration and proteinuria were present after diabetes induction, as evidenced by the increased creatinine clearance and albumin-to-creatinine ratio." (PMID 37240387, 2023). "Compared to those with NMM, men and women with LMM were older, and had significantly greater prevalence of diabetes, higher BMI, serum globulin and triglycerides, lower serum albumin and AGR." (PMID 35501822, 2022). "Diabetes results in the thickening of the capillary basement membrane, deranged microanatomy of capillaries, and albumin leak." (PMID 36059291, 2022). "Fructosamine, glycated albumin, and 1,5-AG have been proposed as alternative markers in patients with diabetes." (PMID 35414081, 2022). "The highest TyG quartile tended to have more percentage of female (p=0.001) and diabetes (p < 0.001), as well as higher levels of albumin (p=0.002) and cholesterol (p < 0.001)." (PMID 36311911, 2022). "Individuals with diabetes had lower albumin and a lower work activity and recreational activity level." (PMID 36387890, 2022). "Linoleic acid was lower in subjects with diabetes (p = 0.018) and correlated with hemoglobin (r = 0.519, p = 0.033) and albumin (r = 0.577, p = 0.015) in subjects with cachexia." (PMID 35269531, 2022). "Diabetes, mechanical ventilation and lower albumin levels on admission were statistically significant predictors of in-hospital mortality in the cohort of patients who received CCP." (PMID 35852992, 2022). "Glycated albumin is not only an indicator for screening and diagnosing of prediabetes and diabetes mellitus, but also a good predictor of diabetes mellitus complicated with macrovascular disease." (PMID 35711907, 2022). "In the univariable analysis, CVC, MVC, AVC, age, diabetes history, CVD history, use of phosphorus-binding medications, use of vitamin D medications, LAD, LVMI, EF, HGB, ALB, β2-microglobulin and iPTH were associated with all-cause mortality." (PMID 35065601, 2022). "Macroalbuminuria, defined as a urinary AER ≥ 300 mg/day (or urine albumin-to-creatinine ratio ≥ 300 mg/g in spot urine specimens), was reported in 14% of children with T1D after a median diabetes duration of 10 years." (PMID 34913986, 2022). "Compared to patients without ICAS, patients with ICAS were older, had higher NIHSS scores, fasting blood glucose, HbA1c, and LDL-C levels, higher proportions of diabetes mellitus, and lower albumin levels (all p < 0.05)." (PMID 36212641, 2022). "The present study showed that Hcy was independently associated with S among older hospitalized adults after adjustment for age, gender, education, smoking, BMI, MNA-SF, ALT, CRP, Hb, ALB, diabetes, kidney disease, and statin use." (PMID 36424548, 2022).
diabetes (continued). "These study findings supports previous study's and confirmed that the elevated levels ofserum adiponectin was identified before excretion of urine albumin, this levels are increased in type 2 diabetes mellitus with normoalbuminuria." (PMID 37654826, 2022). "On multivariable analysis diabetes mellitus (p = 0.004, OR 91.54), mechanical ventilation (p = 0.001, OR 59.07) and lower albumin levels at treatment (p = 0.027, OR 0.74) were significantly associated with increased in-hospital mortality." (PMID 35852992, 2022). "A slight increase in glycated hemoglobin and plasma albumin was observed in patients with diagnosed diabetes mellitus." (PMID 36432489, 2022). "Diabetes, albumin, C-reactive protein, and Kt/V were important indicators of clinical outcomes in HD patients; however, these parameters were not correlated with levels of nAb production in our study." (PMID 35055386, 2022). "Subjects with increased SII level were female, smoker, had elevated age, BMI, SBP, diabetes, hypertension, fasting plasma glucose, triglycerides, waist circumference, and urinary albumin, and decreased HDL-C, ALT, and eGFR levels in our study (all p<0.05)." (PMID 35386695, 2022). "Not only infusions but also albumin nanoparticles have been developed to treat cancer, diabetes, arthritis and hepatitis C." (PMID 36142472, 2022). "Potential cofounders such as age, hypertension, diabetes, and covariants including, sex, serum albumin level, and hemoglobin, significant in the univariate analysis, were adjusted in model." (PMID 35903313, 2022). "Patients with diabetes who had a urinary albumin–creatinine ratio (UACR) of ≥30 mg/g were defined as having DN." (PMID 35631289, 2022). "We matched patients for age, sex, BMI, the proportion of DR, duration of diabetes, the proportion of hypertension, eGFR, initial proteinuria, serum albumin, hemoglobin, glomerular class, IFTA, the proportion with RAAS using." (PMID 36569300, 2022). "In the univariate analysis, sex, diabetes mellitus, postoperative hemoglobin, and postoperative albumin are statistically significant." (PMID 35187165, 2022). "In the univariable analysis, CVC, MVC, AVC, age, diabetes history, CVD history, use of phosphorus-binding medications, use of vitamin D medications, LAD, LVMI, EF, HGB, ALB and β2-microglobulin were associated with CV mortality." (PMID 35065601, 2022). "In their multivariate analysis, diabetes and elevated serum albumin were identified as independent predictors of an attenuated GFR decline." (PMID 35276799, 2022). "Glycated albumin was reported as a reliable biomarker for diabetes screening and diagnosis; however, it was also shown to protect other proteins from glycation and have positive effects on neuronal and glial cells and the overall brain circulation." (PMID 36142472, 2022). "Age, sex, hypertension, BMI, proteinuria, eGFR, serum albumin, diabetes mellitus, diuretic use, allopurinol use and Oxford classification." (PMID 35156903, 2022). "The Cox regression analysis examined factors associated with treatment outcomes, and the univariate analysis demonstrated significantly poorer prognosis in cases with diabetes, low serum albumin, high serum creatinine, and conservative therapy." (PMID 36078614, 2022). "Age, BMI, blood pressure, eGFR, hemoglobin, uric acid, bicarbonate, serum electrolyte concentration and lipid profiles, urine albumin excretion, ALT and diabetes were associated with LVH in univariable analysis." (PMID 35911424, 2022). "In this study, we investigated the potential role and effect of hematopoietic stem cells (HSCs) on maternal diabetes–mediated gastrointestinal (GI) dysfunction and ALB in a mouse model." (PMID 35220596, 2022). "There is still controversy regarding the associations of urinary albumin excretion (UAE) and estimated glomerular filtration rate (eGFR) with atherosclerosis in patients with type 2 diabetes mellitus (T2DM)." (PMID 35413936, 2022).
diabetes (continued). "Factors independently contributing to dementia were advanced age, female sex, presence of diabetes, elevated pulmonary artery pressures and a lower serum albumin." (PMID 36462552, 2022). "Except for age, male gender, lower BMI, diabetes, longer dialysis duration, malnutrition (such as lower serum albumin/pre-albumin), and high-sensitive C-reactive protein (Hs-CRP) were found associated with sarcopenia also in a multivariate logistic regression." (PMID 36458164, 2022). "We need to be more alert to the levels of CRP, ALP, serum lactate, albumin, neutrophils and regular monitoring of blood glucose, once diabetic cancer patients are infected with COVID-19." (PMID 36059615, 2022). "We used urine samples collected from patients with diabetes to quantify urinary albumin concentration, which is essential for the early diagnosis of diabetic nephropathy." (PMID 35955470, 2022). "The Hepamet Fibrosis Score [HFS] is based on age, gender, diabetes mellitus, platelets, albumin, AST, and HOMA [homeostatic model assessment for insulin resistance]." (PMID 35036892, 2022). "These positive effects were objectified by observing certain parameters that undergo critical changes in diabetes: plasma albumin levels and urea and creatinine levels, which were significantly lower in rats receiving Zn compared to the control." (PMID 36363577, 2022). "Glycated albumin (GA) is known to reflect the current inflammatory burden in non-diabetes mellitus (DM) patients." (PMID 35982401, 2022). "Multivariate analysis showed that factors with statistical significance (P < 0.05) included intraoperative dural tear, diabetes, history of rheumatic disease, and preoperative albumin level." (PMID 36050996, 2022). "Nomogram 1 was based on homocysteine (Hcy), high-sensitivity C-reactive protein (hsCRP), and albumin (ALB), and nomogram 2 was based on age, diabetes, hypertension, right-to-left shunt, ALB, prealbumin, hsCRP, and Hcy." (PMID 35756923, 2022). "The subgroup analysis evaluated the heterogeneity of albumin therapy in patients based on age, sex, hypertension, and diabetes." (PMID 36337861, 2022). "The objective of this research aimed to investigate the correlation involving serum albumin with diabetic retinopathy (DR) in patients with type 2 diabetes mellitus (T2DM)." (PMID 35709212, 2022). "There were significant differences between groups for age, sex, C-reactive protein, lymphocyte count, albumin, diabetes, computed tomography findings, mean PNI, and PNI distribution." (PMID 35479742, 2022). "A history of diabetes, preoperative haemoglobin, preoperative albumin, the time from injury to surgery, and the operation time were listed as independent variables, and infection was regarded as the dependent variable." (PMID 36514037, 2022). "In univariate analysis, critical illness was significantly associated with older age, diabetes, CKD and CVD, with lower LN ratio, albumin and eGFR, and with high RDW, CRP, LDH, D-Dimer, and direct bilirubin." (PMID 35223916, 2022). "Model 1 adjusted for gender, age, hypertension, diabetes, uric acid, creatinine, and albumin, the area under the curve was 0.661 (95% CI 0.550–0.773)." (PMID 36224633, 2022). "Three parameters were associated with in-hospital mortality on multivariable analysis, diabetes (p = 0.004, OR 91.54), mechanical ventilation (p = 0.001, OR 59.07) and lower albumin levels on admission (p = 0.027, OR 0.74)." (PMID 35852992, 2022). "The enrolled participants were categorized based on urinary albumin levels, gender, presence of hypertension/diabetes, and smoking and drinking habits." (PMID 35198573, 2022). "The American Diabetes Association (ADA) and Kidney Disease: Improving Global Outcomes (KDIGO) group suggest that the detection of the urinary albumin/creatinine ratio (UACR) and eGFR should be appropriately frequent to better diagnose and treat DKD." (PMID 36210998, 2022).
diabetes (continued). "Selected predictors were the number of hemodialysis sessions, ultrafiltration volume, hemoglobin, BUN, serum sodium, serum calcium, albumin, serum phosphorus, and diabetes." (PMID 36319967, 2022). "Nevertheless, other clinical and laboratory parameters containing diabetes, BMI, hemoglobin, serum albumin, eGFR, and logarithmic transformation of urinary sodium excretion and urinary protein excretion did not relate to LVH." (PMID 35284436, 2022). "On all of the other variables, including body composition (BIA, anthropometry, and handgrip), diabetes control, plasma lipid and lipoprotein levels, liver function test, iron tests, serum albumin and prealbumin, and ammonium, the groups were well matched." (PMID 35684144, 2022). "After univariate Cox regression, diabetes, pre-existing stroke, pre-existing CVD, statins, hemoglobin, serum albumin, HDL-C, low HDL-C group, and diabetes plus low HDL-C group were associated with the first episode of PDRP in patients with PD." (PMID 35488249, 2022). "ACEIs and ARBs are the preferred agents for treatment of high blood pressure in people with diabetes and urine albumin to creatinine ratio (UACR) ≥ 30 or eGFR < 60 mL/min/1.73 m2, as these protect against kidney disease progression." (PMID 35776376, 2022). "The spot urine albumin (Microalbumin) levels were higher in the group with diabetes duration ≥ 10 years compared to < 10 years (83.87 ± 257.20 vs 28.99 ± 52.65 mg/dL, p = 0.004)." (PMID 35794201, 2022). "Although numerous investigations have demonstrated that hypoalbuminemia is connected with inflammation, the correlation between serum albumin and diabetic retinopathy among people with type 2 diabetes mellitus (T2DM) is still unknow." (PMID 35709212, 2022). "Another study evaluated the impact of rosiglitazone on lymphatic function by using technetium-labelled albumin to measure albumin retention and uptake of interstitial albumin by lymphatics in hindquarters of Zucker Diabetic Fatty (ZDF) rats." (PMID 35308247, 2022). "Among patients with low GNRI on admission, patients with worsening nutritional status showed older age, lower BMI, lower frequency of diabetes mellitus, use of aldosterone antagonist, higher sodium level, and lower hemoglobin and albumin levels." (PMID 36297028, 2022). "Increased oxidized serum albumin levels have been reported in patients with hypertension, diabetes mellitus, liver disease, and renal failure, as well as in individuals who have performed strenuous exercise and the elderly population." (PMID 36552593, 2022). "For example, Glucose has the strongest association with Diabetes (HR 1.2), Red Blood Cell Distribution Width (RDW)—with Anemia (HR 1.1), low-density lipoprotein (LDL) with Hyperlipidemia (HR 1.1), and Albumin with Pneumonia (HR 0.96)." (PMID 36535980, 2022). "Standardized mean difference (SMD) of age, DR, duration of diabetes, the proportion of hypertension, eGFR, initial proteinuria, serum albumin, hemoglobin, the proportion of RAAS inhibitor and interstitial fibrosis and tubular atrophy (IFTA) were >10%." (PMID 36569300, 2022). "On the other hand, a significant increase in plasma albumin was observed in patients with diabetes mellitus." (PMID 36432489, 2022). "In particular, the high incidence of nephropathy occurs after suffering diabetes for five-years, and an early indicator thereof is increased urinary albumin excretion." (PMID 35062385, 2022). "In our study, the improvement of GNRI was attributed to improving glycemic control in patients with sarcopenia and diabetes, increased body weight, including skeletal muscle mass, and improving low‐grade inflammation increased the serum albumin levels." (PMID 35290727, 2022). "There were significant differences in male patients in the groups in terms of age, ALB level, eGFR, and smoking history, while females differed in age, ALB level, BMI, eGFR, drinking history, diabetes, and CHD between the low and high SI groups." (PMID 35439963, 2022).